HMGB1 (high mobility group box 1)
Diseases named in the same sentence as HMGB1 in open-access papers (continued):
Sharing a sentence is not in itself a finding about the gene and the disease.
tumor (continued). "Moreover, the high-mobility group 1 (HMGB1) molecule has been associated with progression, invasion, and tumor metastasis; it is abundantly expressed in several tumors and in undifferentiated cells." (PMID 27199982, 2016). "Indeed, the elevated expression of HMGB1 has been detected in of patients with GC and other types of cancer, and its expression is closely associated with tumorigenesis, tumor invasion and metastasis." (PMID 27116470, 2016). "Notably, CD24 and Tim-3 are negative regulators of HMGB1 effects on macrophages and tumor-associated dendritic cells (DCs)." (PMID 26925422, 2016). "Autophagy induction is required and sufficient to cause the release of HMGB1 from dying cells, suggesting that manipulation of autophagy during cancer treatment may influence the immunogenicity of dying tumor cells." (PMID 27294158, 2016). "A number of studies have found that higher expression levels of HMGB1 are closely associated with tumor proliferation, invasion, migration and angiogenesis, as well as anti-apoptotic effects, and HMGB1 can attenuate the role of the body in monitoring tumor invasion and metastasis." (PMID 25574225, 2015). "HMGB1 may cause disordered gene expression, resulting in glial cells obtaining a tumor phenotype and resistance to apoptosis, and ultimately leading to tumorigenesis." (PMID 25574225, 2015). "A previous study found that HMGB1 that is released into the extracellular environment may cause surrounding tumor cells to undergo constant proliferation and induce the regeneration of small blood vessels, thus promoting tumor growth." (PMID 25574225, 2015). "The necrotic tumor cells secrete HMGB1 to cause a cycle of further tumor progression." (PMID 25574225, 2015). "As HOCl-oxidation induces necrotic tumor cell death, it could also cause the release of numerous danger signals such as DNA, RNA, ATP, uric acid, HMGB1, and HSP from the oxidized tumor cells to increase their immunogenicity and to activate DCs." (PMID 26343191, 2015). "This pro-tumorigenic role of HMGB1 may be linked to chronic inflammation, which has been associated with tumor development and progression." (PMID 26486085, 2015). "HMGB1 is also closely associated with tumor drug resistance." (PMID 25574225, 2015). "Necrosis promotes tumour growth and development by releasing the tumour-promoting cytokine high mobility group box 1 (HMGB1); however, the molecular mechanism underlying necrotic cell death remains largely unknown." (PMID 23152075, 2013). "HMGB1 is a chromatin-associated nuclear protein involved in chromatin remodeling and regulation, which may also participate in inflammation and tumor progression." (PMID 22291707, 2012). "Similarly, our study, with immunohistochemistry in a cohort of consecutive 161 previously untreated HCC, demonstrated that high expression of HMGB1 was significantly associated with incomplete tumor encapsulation and advanced TNM stage." (PMID 22747650, 2012). "It indicated that overexpression of HMGB1 was associated with tumor growth and invasion." (PMID 22747650, 2012). "In contrast to tumor-suppressive apoptosis and autophagic cell death, necrosis promotes tumor progression by releasing the pro-inflammatory and tumor-promoting cytokine high mobility group box 1 (HMGB1), and its presence in tumor patients is associated with poor prognosis." (PMID 21917150, 2011). "Overexpression as well as cytoplasmic localization of HMGB1, particularly in conjunction with its receptor for advanced glycation end products (AGEs), is associated with the proliferation and metastasis of many tumor types." (PMID 20579387, 2010). "In addition, the over-expression of HMGB1 in GC is reported to be associated with tumor invasiveness and metastasis." (PMID 19476625, 2009). "Furthermore, PYGB’s positive correlation with HMGB1, a protein involved in regulating inflammation and immune responses, suggested its potential involvement in the inflammatory processes associated with tumor progression." (PMID 40458414, 2025).
tumor (continued). "Additionally, the study also demonstrated that exogenous lactate treatment can induce NETs formation.As a complex composed of various proteases (NE, MPO, HMGB1, etc.)and DNA, NETs and their associated components have been shown to significantly impact tumor metabolic reprogramming." (PMID 39849606, 2025). "Notably, ferroptotic demise of tumor cells has been identified as a significant source of danger-associated molecular patterns (DAMPs), encompassing molecules such as HMGB1, DNA, ATP, as well as lipid oxidation products like LTB4 and PGE2, particularly in the context of cancer therapy." (PMID 38349553, 2024). "Moreover, HMGB1 gene polymorphisms may influence tumor size and metastasis, particularly in Han Chinese populations." (PMID 39830522, 2024). "Moreover, chemotherapy has been found to elevate the secretion of damage-associated molecular patterns (DAMPs) and high-mobility group box 1 (HMGB1) from apoptotic/necrotic tumor cells, which, consequently, may help with the CAR-T-cell function." (PMID 38201467, 2023). "Finally, HMGB1 can also act as an alarmin or damage-associated molecular pattern (DAMP) by interacting with RAGE or Toll-like receptors (TLR) when secreted into the tumor microenvironment." (PMID 37627239, 2023). "Specifically, some dying tumor cells release multiple danger signals or damage-associated molecular patterns (DAMPs), including high mobility group protein B1 (HMGB1), calreticulin and ATP, which dominantly represent immunogenic features and may contribute to the immunotherapy." (PMID 37553698, 2023). "HMGB1 is closely associated with cell survival and proliferation and may be directly involved in tumor cell metastasis development thanks to its ability to promote cell migration, enhance the adhesive properties of cells, and rearrange components of the extracellular matrix." (PMID 36012593, 2022). "HMGB1 is associated with and may be a potential marker in the prognosis of various tumours." (PMID 35379200, 2022). "Indeed, HMGB1 is closely associated with cell survival and proliferation and may be directly involved in tumor cell metastasis development thanks to its ability to promote cell migration." (PMID 36012593, 2022). "In addition to its nuclear functions, HMGB1 in the cytoplasm acts as an extracellular signaling molecule that is closely associated with inflammation, cell proliferation and differentiation, and tumor progression." (PMID 34778055, 2021). "However, it should be noted that alternative mechanisms beyond exosomal HMGB1 underlying local tumor growth may exist owing to the presence of platelets within tumor tissues." (PMID 33669632, 2021). "However, further studies are required to determine whether plasma HMGB1 levels are associated with tumor mass measurements (Response Evaluation Criteria in Solid Tumors) following treatment." (PMID 34966671, 2021). "Due to the stress response after the irradiation of the tumor cells, the damaged and dying cells release damage-associated molecular patterns (DAMPs) including heat shock protein 70 (Hsp70), calreticulin, adenosine-5′-triphosphate (ATP), and high mobility group protein B1 (HMGB1)." (PMID 34768644, 2021). "Tumor-associated myeloid cells represented by tumor-associated macrophages (TAMs) and myeloid-derived suppressor cells (MDSCs) express multiple receptors of HMGB1 and play an important role in supporting cancer growth and survival, angiogenesis, metastasis as well as immunosuppression." (PMID 34257571, 2021). "In a further exploration of the molecular mechanisms underlying the hypoxia‐induced aggressive tumor phenotype of BC, we found that, as a potential tumor suppressor, miR‐141–3p counteracted hypoxia‐induced migration and suppressed the hypoxia‐activated HMGB1/HIF‐1α pathway." (PMID 32436353, 2020). "Thus, the results indicated that autophagy-deficient tumor cells had released HMGB1." (PMID 32382012, 2020).
tumor (continued). "Moreover, some of the damage-associated molecular patterns (DAMPs) such as the high mobility group box 1 (HMGB1) derived from tumor cells or TME could also promote the CSCs phenotype via innate immune signaling." (PMID 32843056, 2020). "Released high-mobility-group box 1 from chemo- or radiotherapy-treated tumor cells promote the maturation and activation of DCs, resulting in an efficient processing and presentation of tumor-associated antigens and the stimulation of potent tumor-directed T-cell responses." (PMID 30984181, 2019). "In particular, a multifaceted response to tumor antigens released following necrosis and apoptosis results from exposure to PAMPs, danger associated molecular patterns (DAMPs: such as heat shock proteins, uric acid, calreticulin, HMGB-1), and cytokines (such as IFN 1, interleukin 12, and TNF α)." (PMID 30514385, 2018). "On one hand, loss of intracellular HMGB1 increases chromosomal instability and telomere attrition, whereas increased extracellular nuclear DAMPs (e.g., nucleosome) in HMGB1-deficient cancer cells cause an excessive inflammation response in the tumor microenvironment." (PMID 28374746, 2017). "Our finding that HMGB1 overexpression is associated with poorer prognosis in cancer patients indicates this gene may have the potential to become a critical molecular target for tumor therapy." (PMID 27391431, 2016). "HMGB1 is an abundant multifunctional protein possessing diverse biological activities in normal cells, and has been the subject of intense investigation in recent cancer research being implicated in tumour formation, progression, metastasis and response to chemotherapeutics (reviewed)." (PMID 27323825, 2016). "Thus, chemotherapeutic agents can universally cause tumor cell death, accompanied by HMGB1 release." (PMID 26469759, 2015). "In experiments to further help determine whether HMGB1 regulates VEGF-A in tumour angiogenesis, we applied the associated antibodies to co-cultured ECs, and VEGF-A concentrations were decreased by 2G7 mAb, TLR4 Ab and RAGE Ab, as demonstrated in Western blot analyses." (PMID 26099505, 2015). "Therefore, our results might be caused by the multiple factors in addition to HMGB1 that contribute to distant metastasis in contrast to tumor expansion and local invasion." (PMID 19476625, 2009). "Immunofluorescence staining indicated an elevation in the expression levels of calreticulin (CRT) and high-mobility group protein B1 (HMGB1) within tumor tissues following APPF+laser treatment, thereby promoting dendritic cells (DCs) maturation." (PMID 41355972, 2026). "Compared with RT alone, RCL@Pd@CuZ + RT significantly increased the levels of CRT and HMGB1 in the tumor, confirming the occurrence of a more intense ICD." (PMID 41424843, 2026). "High mobility group box 1 (HMGB1), a prototypical alarmin and chromatin-binding protein, has emerged as a critical mediator of tumour-associated inflammation and immune regulation." (PMID 41645802, 2026). "Lactylated CREB1 promotes HMGB1 transcription and subsequent exosomal secretion into the tumor microenvironment." (PMID 42212318, 2026). "In cancer, HMGB1 has been described as having both tumour-promoting and tumour-suppressing features, possibly dependent on the form of HMGB1 released into the tumour microenvironment." (PMID 42067772, 2026). "This nanotherapeutic approach, particularly when combined with cisplatin, potently suppressed tumor growth in vivo and reduced serum exosomal HMGB1 levels, effectively reversing chemoresistance." (PMID 42212318, 2026). "High mobility group proteins (HMGA1, HMGA2, HMGB1) and miR-106a-5p are involved in tumor progression, but their interplay in UC remains incompletely understood." (PMID 41828319, 2026). "The following immunohistochemistry revealed that HMGB1 was translocated from the nucleus to the cytoplasm of the BNCT-treated tumor cells, indicating that its release was associated with cell death." (PMID 41328345, 2026).
tumor (continued). "Exosomal HMGB1 markedly enhanced tumour cell proliferation, motility and self-renewal capacity, while promoting chemoresistance and immune evasion." (PMID 41645802, 2026). "Another study demonstrated that miR-5683 interacts with HMGB1, contributing to the tumor-suppressive effect of Aloin in GC cells." (PMID 41568058, 2026). "In this system, HA1 was designed to improve tumor-cell recognition and tumor-site accumulation, whereas HMGB1 was introduced to promote macrophage-tumor cell interaction and facilitate phagocytic engagement." (PMID 42292856, 2026). "Our research results indicated that high-dose proton irradiation trigger the rejection of distal tumor colonization through a signaling pathway that depends on HMGB1." (PMID 41641047, 2026). "This autophagic release of HMGB1 into the extracellular space can powerfully influence tumor cell survival, stromal communication, and ultimately, the therapeutic response, creating a self-reinforcing cycle of resistance." (PMID 41465435, 2025). "The activation of GSDMC in tumor cells promoted tumor progression through facilitating the release of HMGB1 and CXCL2‐dependent recruitment of MDSCs to orchestrate the immunosuppressive microenvironment." (PMID 40213993, 2025). "Using receiver operating characteristic analysis, the cut-off level of serum HMGB1 to predict tumor response was determined to be 3.83 ng/mL." (PMID 39853458, 2025). "Simultaneously, RT upregulates FAS (death receptor), MHC class I, translocation of calreticulin to tumor cell surfaces, and increases the release of HMGB1 from dying tumor cells." (PMID 40141437, 2025). "Fotoenticine has also demonstrated potential to induce ICD by exposing calreticulin and promoting the release of ATP and HMGB1, thereby stimulating the immune system against the tumor." (PMID 40916083, 2025). "Through cellular experiments, we confirmed the role of HMGB1 in promoting the malignant behavior of tumor cells." (PMID 40975711, 2025). "Since HMGB1 can be recognized by TLR4 on immune cells and activate anti-tumor immunity, we used Tlr4-/- mice to block extracellular HMGB1 triggered antitumor immunity." (PMID 40557162, 2025). "To further illustrate the context-dependent nature of HMGB1’s function, we have summarized its oncogenic and tumor-suppressive roles across various cancer types with representative examples." (PMID 40969278, 2025). "HMGB1 produced by the ferroptotic tumor cells can also promote M1 polarization through the HMGB1-AGER interaction." (PMID 40064873, 2025). "Upon induction, ferroptotic tumor cells release damage-associated molecular patterns (DAMPs) such as calreticulin (CRT), ATP, and high-mobility group box 1 (HMGB1), which act as “find-me” and “eat-me” signals to recruit dendritic cells (DCs)." (PMID 40887613, 2025). "Specifically, HMGB1 levels are elevated in cancer patients, both locally in tumor cells and systemically in serum." (PMID 40007542, 2025). "Disruptions in autophagy can drive inflammasome‐mediated tumor progression through HMGB1 activation." (PMID 40671967, 2025). "This overview underscores the complexity of HMGB1-mediated signaling within the tumor microenvironment and highlights the need for tailored therapeutic approaches based on its distinct functional states." (PMID 40969278, 2025). "A significant increase in CRT and HMGB1 of tumor tissues after 7 d of 131I-Mn/SAE@M treatment was found, indicating the initiated ICD pathway." (PMID 40968370, 2025). "Following irreversible electroporation (IRE), a sublethal electric pulse can promote tumor recurrence by triggering HMGB1 release." (PMID 41465435, 2025). "Increasing evidence indicates that HMGB1 contributes to therapeutic resistance through multiple molecular mechanisms, with its functional impact exhibiting notable tumor-type specificity." (PMID 40969278, 2025).
tumor (continued). "Teniposide has been reported to induce the expression of the MC38 and CT26 tumor cell immunogenic cell death marker HMGB1, T cell activation, and DC maturation." (PMID 40643531, 2025). "Intracellular hyperthermia has been proven to stimulate the release of tumor antigens and pro-inflammatory cytokines, including heat HSPs, adenosine triphosphate (ATP), and high mobility group protein 1 (HMGB1)." (PMID 40688079, 2025). "In this context, tumor cell-released autophagosomes (TRAPs) are decorated with elevated levels of surface HMGB1." (PMID 41465435, 2025). "Serum HMGB1 levels reflect tumor cell lysis and ICD-driven DC activation, whereas CXCL9/CXCL10 gradients predict Batf3-dependent CD103+ DC migration and T-cell priming." (PMID 40989107, 2025). "Tumor cells also release adenosine triphosphate (ATP), high mobility group box 1 protein (HMGB1), and calreticulin, which are recognized by cell surface receptors P2X7, CD91, and toll-like receptor 4 (TLR4), respectively, on DCs." (PMID 41375050, 2025). "Responders exhibit a dominant signature characterized by IL1B, MIF, CXCL5, and HMGB1—indicating an inflamed, neutrophil-rich tumor microenvironment (TME) that is primed for antitumor immunity." (PMID 40723289, 2025). "HMGB1 activates diverse inflammatory signaling pathways, driving inflammatory cell infiltration and cytokine release to shape a tumor‐promoting microenvironment." (PMID 41354099, 2025). "CRT is a factor that promotes the uptake of tumor cells by macrophages, increases phagocytosis, and activates tumor immunity, whereas HMGB1 acts as an immunosuppressive protein functioning outside the cell." (PMID 41463178, 2025). "Our previous work indicates that the combination of RT and chemotherapy with docetaxel alters the immune phenotype of HNSCC tumor cells, characterized by increased surface expression of CD137-L and release of HMGB1 of specifically HPV-positive tumor cells." (PMID 40883442, 2025). "circ_0005909 binds to miR-936 to upregulate HMGB1, promoting epithelial–mesenchymal transition and tumor metastasis." (PMID 41296391, 2025). "Although an increased expression of ICD-related molecules is observed in vitro, we observe that the tumor growth of Cdk2-/- cells with increased HMGB1 release in Tlr4-/- mice remained similar to that in C57 mice." (PMID 40557162, 2025). "Given previous findings suggesting a role of HMGB1 in tumor angiogenesis, we further investigated the influence of IFNG expression on this process." (PMID 39945555, 2025). "In summary, HMGB1 exerts dual anti-tumor effects by both directly suppressing tumor growth through cytotoxic mechanisms and enhancing immune-mediated anti-tumor responses." (PMID 40969278, 2025). "The role of HMGB1 in tumor metastasis has been demonstrated in several cancer types, including lung, colon, and liver cancers." (PMID 40331953, 2025). "This creates a feed-forward loop, as the released HMGB1 can further stimulate autophagy in the CAFs themselves, sustaining the activated state of the tumor stroma." (PMID 41465435, 2025). "Following TAK-242 treatment to inhibit TLR4 signaling, the HMGB1-induced M1 macrophage polarization stimulated with the supernatants from ADVNE− or ADVPPE-treated tumor cells was abrogated." (PMID 40082916, 2025). "These collective findings suggest that HMGB1 enhances repair kinetics following genotoxic insult, facilitating tumor cell survival under therapeutic stress." (PMID 41465435, 2025). "HMGB1, a classic inflammatory damage molecule, is released by dying tumor cells, and DAMPs, which bind to TLR4 or RAGE innate immune receptors on DC cells, mediate innate immune recognition of cancer." (PMID 40524208, 2025). "In the TME, Tim-3 on tumor-infiltrating DCs binds to HMGB1, blocking the transport of nucleic acids into endosomes and suppressing innate immune responses to tumor-derived nucleic acids." (PMID 40814339, 2025).